CRP (C-reactive protein)
Diseases named in the same sentence as CRP in open-access papers (continued):
Sharing a sentence is not in itself a finding about the gene and the disease.
endothelial dysfunction (continued). "The mechanism behind CRP inhibition may be that CRP inhibits the biological activity and expression of endothelial nitric oxide synthase in endothelial progenitor cells, thereby inhibiting the synthesis of NO and leading to endothelial dysfunction." (PMID 36386339, 2022). "More importantly, endothelial dysfunction of resistance, but not conduit arteries has been demonstrated to be associated with increased C-reactive protein and E-selectin levels after adjustment for cardiovascular risk factors in a large cohort of elderly subjects." (PMID 34095261, 2021). "Another relevant clinical finding of this study is that endothelial dysfunction may contribute to the development of type 2 DM, preceding—rather than following—its onset, as a consequence of a low-grade inflammatory state as documented by an hs-CRP increase." (PMID 34201832, 2021). "Moreover, in HFD-fed rabbits, especially in carotid PVAT(+) groups, CRP (C-reactive protein) significantly promoted endothelial dysfunction, which might be mediated by activating the inflammatory response of adipose tissue." (PMID 33391033, 2020). "Chronic periodontal infection is characterized by elevation of CRP and inflammatory cytokines in the systemic circulation, so it is possible that systemic inflammation in patients with PD can potentially accelerate endothelial dysfunction, plaque buildup and CHD events." (PMID 33519515, 2020). "Furthermore, several studies have reported that an intensive periodontal treatment resulted not only in a temporary increase in serum levels of CRP and IL-6, but also in a significant improvement of endothelial dysfunction indexes at six months after active periodontal therapy." (PMID 31817862, 2019). "However, the most compelling data implicating CRP as a determinant of endothelial dysfunction has been obtained from studies demonstrating that human recombinant CRP reduced basal and stimulated nitric oxide (NO) release from arterial and venous endothelial cells." (PMID 31151201, 2019). "Higher levels of CRP may increase blood pressure by reducing nitric oxide production in endothelial cells, resulting in vasoconstriction and increased production of endothelin-1 which are the markers for endothelial dysfunction." (PMID 26989902, 2016). "Besides increasing exercise capacity in these patients, physical exercise also improves endothelial dysfunction and decreases certain inflammatory mediators, such as C-reactive protein, superoxide dismutase, 8-isoprostane, and CD34/KDR+ endothelial progenitor cell count." (PMID 24616817, 2014). "Proinflammatory cytokines are released into the bloodstream and promote the release of CRP from the liver, which could result in an inflammatory response, platelet aggregation, and endothelial dysfunction, and may ultimately contribute to the development of CVD and metabolic disorder." (PMID 25078288, 2014). "Conclusion: eventhough the inverse association between serum 25(OH)D and CRP does not infer causality, lower serum 25(OH)D may increase risk for inflammation and endothelial dysfunction." (PMID 23029606, 2012). "Emerging biomarkers of endothelial dysfunction, including neopterin, osteoprotegerin, fetuin-A, homocysteine, leptin, adiponectin, PAI-1, CRP, IL-6, and CECs, provide additional understanding of the pathophysiology of endothelial damage." (PMID 40529825, 2025). "However, CRP is a non-specific marker of inflammation, and the inclusion of endocan, which is more directly linked to endothelial dysfunction, may improve risk stratification for PAD in this population." (PMID 40282868, 2025). "In RA, early endothelial dysfunction is driven by inflammatory cytokines including tumor necrosis factor-α (TNF-α), interleukin (IL)−1, and is reflected by increased C-reactive protein (CRP)." (PMID 41015607, 2025). "For instance, does AIP correlate with markers of systemic inflammation such as C-reactive protein (CRP), or with early indicators of endothelial dysfunction?" (PMID 40747310, 2025).
endothelial dysfunction (continued). "The studies reviewed highlight a multifactorial process involving inflammatory agents such as CRP, S100 proteins, IL-18, IL-33, TNF, and osteopontin, alongside impaired HDL function, endothelial dysfunction, and altered immune cell profiles." (PMID 40943152, 2025). "Moreover, we focused primarily on inflammatory and hematologic indices; the addition of emerging markers of endothelial dysfunction (e.g., endothelin-1, von Willebrand factor) or systemic inflammation (e.g., interleukin-6, C-reactive protein) may enhance prognostic stratification." (PMID 41303423, 2025). "The current body of evidence reveals several consistent patterns, most notably the strong association between chronic periodontal inflammation and systemic endothelial dysfunction, mediated by proinflammatory cytokines such as IL-6, TNF-α, and CRP." (PMID 41294894, 2025). "Upregulated proteins (e.g., CRP, C9, APOC1) correlated with visceral adiposity, systemic inflammation, and endothelial dysfunction." (PMID 40981199, 2025). "Endothelial dysfunction markers (VCAM-1, ICAM-1, sICAM-1/sVCAM-1),platelet activation (P-selectin), clotting factors (D-dimer, fibrinogen),hs-CRP (chronic inflammation), homocysteine (vascular stress marker)." (PMID 41031540, 2025). "The mechanism includes increased systemic inflammation (C-reactive protein, IL-6, and TNF-α), hormone imbalance, and endothelial dysfunction." (PMID 41153819, 2025). "Increased plasma levels of interleukin-6 (IL-6), C-reactive protein (CRP), and tumour necrosis factor-α (TNF-α) pinpoint systemic inflammation and contribute to endothelial dysfunction in cSVD." (PMID 40699631, 2025). "Cytokines such as interleukin-1β (IL-1β) and interleukin-6 (IL-6) further stimulate hepatic production of acute-phase proteins such as C-reactive protein (CRP), contributing to endothelial dysfunction in systemic blood vessels." (PMID 41444986, 2025). "It was discovered that endothelial dysfunction exhibited a positive linear connection with erythrocyte sedimentation rate (ESR) and C-reactive protein (CRP) when contrasted with traditional inflammatory indicators such as ESR and CRP." (PMID 39310576, 2024). "In summary, CRP and HDL are crucial markers of inflammation and endothelial dysfunction, respectively, each playing significant roles in the promotion and inhibition of inflammatory responses." (PMID 39634189, 2024). "These markers include indicators of endothelial dysfunction (VCAM-1, ICAM-1, MCP-1) and an acute-phase reactant (CRP)." (PMID 39144845, 2024). "Markers of inflammation (CRP, LDH, IL6), endothelial dysfunction (ICAM1, VCAM1, E-selectin), coagulation (fibrinogen) and fibrinolysis (D dimers) are used in assessing disease severity, prognosis and treatment options." (PMID 38474287, 2024). "Systemic inflammation, evidenced by increased levels of pro-inflammatory cytokines such as IL-6 and TNF-α, together with biomarkers of endothelial dysfunction such as PAI-1 and CRP, demonstrate a chronic inflammatory state present in MetS." (PMID 39728125, 2024). "These pathogens elevate levels of systemic inflammatory markers like C-reactive protein (CRP), which can lead to endothelial dysfunction and increase the vulnerability of blood vessels to atherosclerotic changes." (PMID 39064298, 2024). "Enhanced levels of these cytokines, C-reactive protein (CRP), and homocysteine in the context of IBD can also contribute to endothelial dysfunction." (PMID 38018203, 2023). "We had measurement of biomarkers for endothelial dysfunction (serum ADMA, high sensitivity-CRP and ABI measurement) and were unable to longitudinally assess the relationship between changes in endothelial dysfunction and renal function." (PMID 37596359, 2023). "Inflammatory cytokines, such as interleukin-1β (IL-1β), tumor necrosis factor-α (TNF-α), and C-reactive protein (CRP), promote endothelial dysfunction, leukocyte recruitment, and smooth muscle cell migration, proliferation, and apoptosis." (PMID 37298518, 2023).
endothelial dysfunction (continued). "It appears that the treatment of obese rats with ZnONPs inhibits the progression of endothelial dysfunction, as evidenced by a reduction in the aortic tunica thickening, fibroid necrosis in the aorta, foam cells, and plasma levels of MCP-1, resistin, and CRP." (PMID 37749096, 2023). "The increase in CRP and IP-10 in these patients further validates T1DM as a chronic inflammatory state that is characterized by vascular and endothelial dysfunction as a major contribution to the development of CVD." (PMID 37569355, 2023). "Systematic inflammation and circulating cyto- and chemokines including C-reactive protein, IL-6, IL1β, and TNFα fuel CVD through endothelial dysfunction, altered vascular tone, enhanced plaque formation, and coagulation." (PMID 36564799, 2022). "CRP and fibrinogen are related to metabolic and cardiovascular disease (CVD) (partly via endothelial dysfunction) and to mortality." (PMID 36095032, 2022). "Markers of endothelial dysfunction (ICAM1, VCAM, VEGFR3, thrombomodulin) and inflammatory response (CRP, MPO) were also noted to progressively increase with rising altitude in both groups, more prominently so in ICs and has been reported earlier by us." (PMID 37384264, 2022). "It has previously been established that systemic inflammatory mediators (e.g., C reactive protein (CRP), TNF-α) can contribute to the development of HF, and inflammation can induce cardiomyocyte apoptosis and endothelial dysfunction." (PMID 35350538, 2022). "IL-6 also triggers hepatic synthesis of CRP, while TNF-α is more involved in the activation of inflammatory cytokine, endothelial dysfunction and induction of bone resorption." (PMID 33676486, 2021). "Meta-analyses reported elevated circulating markers of inflammation, e.g. interleukin 6 (IL-6) and C-reactive protein (CRP), and markers of endothelial dysfunction, e.g. E-selectin, in individuals with SVD." (PMID 34055930, 2021). "As we experience a drop in glomerular filtration, we have a higher level of inflammation and endothelial dysfunction through changes in a series of markers, such as levels of nitric oxide, ADMA, CRP, among others." (PMID 34433133, 2021). "Another study in people with rheumatoid arthritis showed an inverse relationship between C-reactive protein and SBP, partly explained by endothelial dysfunction that reduces vasomotor control and BP regulation." (PMID 34138851, 2021). "We measured the levels of high-sensitivity C-reactive protein (hs-CRP), intercellular adhesion molecule 1 (ICAM-1), and vascular cell adhesion molecule 1 (VCAM-1) as markers of inflammation and endothelial dysfunction." (PMID 32433661, 2020). "In earlier observations, native CRP has been shown to induce pro-inflammatory cytokine release from endothelial cells (VCAM-1, ICAM-1, and E-selectin) and monocytes (MCP-1) and evoke endothelial dysfunction and monocyte adhesion to the endothelium." (PMID 31151201, 2019). "High levels of serum inflammatory cytokines and markers such as tumor necrosis factor-α (TNF-α), interleukin-6 (IL-6), C-reactive protein (CRP), and alpha-1-acid glycoprotein (AGP) have been correlated with the endothelial dysfunction." (PMID 31737180, 2019). "Nevertheless, no changes were observed in the concentrations of markers related to endothelial dysfunction [VCAM, E-selectin, and advanced glycation endproducts (AGEs)] or inflammation (hs-CRP, IL-6, and TNF-α)." (PMID 31068933, 2019). "We therefore measured the circulating levels of the main pro-inflammatory mediators that can be directly affected by Mg/Ca and by endothelial dysfunction, including TNF-α, IL-6 and CRP: they were all substantially higher in AAD patients than controls." (PMID 28070203, 2017). "Furthermore, endothelial dysfunction and the following arterial stiffness have been related to the synergistic effect of smoking with inflammatory molecules of interleukin-6 (IL-6), C-reactive protein (CRP), and cyclooxygenase-1 and cyclooxygenase-2 (COX-1 and COX-2)." (PMID 26885247, 2016).
endothelial dysfunction (continued). "In patients with endothelial dysfunction, FBG, HbA1C, hs-CRP and Hcy were significantly higher than those in patients with normal endothelial function (P<0.05 for all)." (PMID 26150839, 2015). "Certain markers of endothelial dysfunction (ICAM-1 and VCAM-1), inflammation (C-reactive protein) and thrombotic activity (PAI-1) are also reported here for the first time." (PMID 25115868, 2014). "This phenomenon has been linked to induction of complement activation, leukocyte infiltration, and modification of vascular response to vasodilators, representing a shared pathway for CRP and oxidized LDL (LDL-ox) in endothelial dysfunction." (PMID 27433484, 2014). "Markers of endothelial dysfunction and inflammation include tumour necrosis factor-alpha (TNF-α), the interleukins (IL) and C-reactive protein (CRP)." (PMID 29062730, 2012). "The biomarkers used in our multimarker panels (MR‐proADM, CRP, D‐dimer, and LDH) are not variant‐specific, but instead reflect host pathophysiological responses such as systemic inflammation, endothelial dysfunction, and coagulation abnormalities." (PMID 40761043, 2025). "Empirical evidence suggests that both short and long sleep durations are associated with elevated levels of inflammatory markers, such as C-reactive protein (CRP) and interleukin-6 (IL-6), which contribute to endothelial dysfunction and arterial plaque formation." (PMID 40391016, 2025). "Elevated levels of IL-6, TNF-alpha, CRP, MCP-1, and endothelial dysfunction biomarkers such as oxidized HDL and soluble ICAM-1 supports the role of inflammation in the development and persistence of visceral adiposity and systemic inflammation in this population." (PMID 40722634, 2025). "Microvascular injury, oxidative stress and endothelial dysfunction promote cytokine release and hepatic synthesis of acute-phase proteins (Fib and CRP), thereby elevating inflammatory indices even in non-glomerular CKD etiologies." (PMID 41302152, 2025). "Other surveys have shown that dietary AGEs alone do not significantly affect serum CML, sRAGE and CRP, inflammatory markers or endothelial dysfunction." (PMID 39201577, 2024). "The hs-CRP level and AUER were the baseline markers for endothelial dysfunction." (PMID 39064476, 2024). "In our study, the result of correlation coefficient of inflammatory markers (IL-6, IL-8) and endothelial dysfunction marker (ICAM, VCAM) with biochemical marker AST, CKMB and CRP of overall (IL-6, IL-8, ICAM, VCAM × AST, CKMB and CRP) had a statistical significantly positive correlation." (PMID 38961103, 2024). "Even in the absence of CVD, it was found that increased plasma CRP concentrations correlate with endothelial dysfunction markers in T1DM." (PMID 37569355, 2023). "In particular, the endothelial dysfunction disrupts the regulatory balance by decreasing nitric oxide and promoting an increase of interleukin-6 (IL-6), tumor necrosis factor (TNF-α), and blood levels of CRP." (PMID 37568542, 2023). "Increased value of hs-CRP is a strong indicator of endothelial dysfunction, evident in even the non-diabetic population, with increased cardiovascular risk or with chronic kidney disease." (PMID 36010052, 2022). "Upon endothelial damage, there is an increase in proinflammatory molecules such as interleukin-1 (IL-1), interleukin-6 (IL-6), tumor necrosis factor alpha (TNF-α) and C-reactive protein (CRP) leading to a proinflammatory endothelium and endothelial dysfunction." (PMID 35455027, 2022). "Determining the concentration of ADMA and CRP in common clinical practice could indicate a possible, more aggressive manifestation of the APS clinical picture, and emphasize the impact of endothelial dysfunction." (PMID 36293156, 2022).
endothelial dysfunction (continued). "Excess of UA has paradoxically pro-oxidant effects in the vascular cells, impaired nitric oxide production, increased cytokines (IL 1β, IL 6, TNF α, CRP, MCP-1), and platelet-derived growth factors expression, leading to endothelial dysfunction and VSMC proliferation." (PMID 36060948, 2022). "Increased carotid intimal thickness, wall stiffness, and endothelial dysfunction observed in patients with IBD may be due to the increase in circulating inflammatory cytokines and CRP." (PMID 35770006, 2022). "In OSA patients, repeated oxygen desaturations and subsequent endothelial dysfunction induce the release of strong proinflammatory biomarkers, particularly tumor necrosis factor alpha (TNF-α), interleukin-6 (IL-6), C-reactive protein (CRP), leptin, and reactive oxygen species (ROS)." (PMID 34349888, 2021). "In the course of IBD, increased concentrations of pro-inflammatory cytokines, such as C-reactive protein (CRP) and homocysteine, may lead to endothelial dysfunctions and the development of CVD." (PMID 34444821, 2021). "Low-grade systemic inflammation associated with PCOS is indicated by the high levels of inflammatory markers such as interleukin-18 (IL-18), C-reactive protein (CRP), white blood count, and monocyte chemoattractant protein-1 (MCP-1), along with increased oxidative stress and endothelial dysfunction." (PMID 33679617, 2021). "Biomarkers of endothelial dysfunction and low-grade inflammation were not modified (CRP, serum amyloid A, IL-6, IL-8, TNF-α, and soluble intercellular adhesion molecule-1) and neither was FMD." (PMID 31068933, 2019). "The content of the circulating adhesion molecule vCAM-1 was positively correlated with the levels of CRP (r = 0.42), leptin (r = 0.31), TNF-a (r = 0.35) and IL-6 (r = 0.52), indicating the participation of proinflammatory molecules in the formation of endothelial dysfunction (p < 0.05)." (PMID 30871567, 2019). "Since CRP did not normalize with albumin infusion, this suggests that the relationship between low S-Alb levels and endothelial dysfunction is intermediated by inflammation." (PMID 29298330, 2018). "This indicates early endothelial dysfunction nor inflammation marker such as high-sensitivity CRP do not influence the expression of s-Podxl." (PMID 29321582, 2018). "CRP levels correlated inversely with alpha diversity measures but not with markers of endothelial dysfunction." (PMID 29712976, 2018). "In our study, NPY, CA, AngII, ET-1, CRP, IL-6, and TNF-α increased while MT decreased after SD, which is characteristic of the beginning of myocardial injury due to hormone disorders, inflammation, and endothelial dysfunction." (PMID 28479928, 2017). "In addition, RYR in combination with antioxidants has been demonstrated to reduce high sensitivity C-reactive protein (hs-CRP) and endothelial dysfunction." (PMID 28257063, 2017). "Significant disease associations have been shown between vascular function, high sensitive-CRP (hs-CRP), and interleukin-6 (IL-6) in RA and SLE patients, suggesting a link between systemic cytokine overexpression and endothelial dysfunction, an early event in the development of CVD." (PMID 25648164, 2015). "Despite the significant increase in vitamin D levels in the cholecalciferol group, there was no reduction in markers of endothelial dysfunction including D-dimer, von Willebrand factor, fibrinogen and interleukin (IL) 8 or C reactive protein." (PMID 25006678, 2014). "Multiple epidemiological and mechanistic studies have shown that CRP is not just a marker but rather an active mediator for endothelial dysfunction, arterial thrombosis and atherogenesis." (PMID 24466039, 2014). "Probably the most relevant finding of our study was that, in absence of clear vascular remodelling or vasodilatadory endothelial dysfunction, increased levels of endothelium-release biomarkers (sVCAM-1, hs-CRP and TNF-α) were observed in patients with FD." (PMID 24207059, 2013).